NLRP1 (NLR family pyrin domain containing 1)
Diseases named in the same sentence as NLRP1 in open-access papers (continued):
Sharing a sentence is not in itself a finding about the gene and the disease.
infection (40 papers, 2013 to 2025). The state of being infected such as from the introduction of a foreign agent such as serum, vaccine, antigenic substance or organism. "There are many other studies that have reported the involvement of NLRP1 inflammasome in diverse infection-associated immune responses." (PMID 38644450, 2024). "In contrast to humans, mice express several NLRP1 alleles and particularly NLRP1b confers susceptibility to infection by Bacillus anthracis." (PMID 32640751, 2020). "On that note, inbred rat strains vary widely in their susceptibility to infection by T. gondii, and these differences are controlled by Nlrp1 30,31,39,40." (PMID 31383852, 2019). "In the absence of LPS priming, Type II strain-infected BMDMs did not produce IL-1β (data not shown), but low levels of IL-18 were measurable by 6 h (PRU) and 24 h (76K) of infection in an NLRP1 variant-dependent manner." (PMID 24626226, 2014). "As GBPs are known to be involved in pyroptosis, and Tg infection of rodent macrophages causes pyroptosis via NLRP1 and NLRP3, we reasoned that human macrophages infected with Tg might also undergo pyroptosis." (PMID 31268602, 2019). "Infection with SFTSV led to reduction of NLRP1/CARD8 NT and MG132 restored NLRP1 NT, indicating that N-terminal functional degradation occurs in a proteasome-dependent manner during activation of the NLRP1 and CARD8 inflammasome." (PMID 40608794, 2025). "Here, we report that a tick-borne bunyavirus SFTSV infection activates the NLRP1 inflammasome in primary keratinocytes and the CARD8 inflammasome in macrophages in a similar manner by targeting the ternary inhibitory complex, respectively." (PMID 40608794, 2025). "Adoptive mixed neutrophil transfer experiments further demonstrate that NLRP1-driven neutrophil pyroptosis plays a crucial role during the first days of infection." (PMID 39250503, 2024). "NLRP1 can act as a “tripwire” against certain viruses upon infection of human keratinocytes or other epithelial cells, which is activated after proteolytic cleavage in N-NLRP1 by viral 3C proteases." (PMID 38920661, 2024). "In other viral infections, such as in Picornaviridae family-related infections and double-stranded RNA Semliki Forest virus infections, NLRP1 has been identified as a sensor that triggers and regulates the protective innate immune response." (PMID 38644450, 2024). "Significantly less cell death was observed in BMDMs transfected with Itch or Nlrp1 sgRNAs after infection with Toxoplasma compared with BMDMs transfected with Cas9 protein alone or Cas9 protein with scrambled sgRNAs (targeting E. coli LacZ)." (PMID 38376248, 2024). "Five weeks post-infection, Nlrp1-/- mice developed a significantly larger lesion score than control C57BL/6 mice." (PMID 39250503, 2024). "The parasite specifically activates the LEW rat NLRP1 inflammasome, resulting in macrophage pyroptosis and subsequent clearance of the infection (15, –, 17)." (PMID 38376248, 2024). "Nevertheless, these findings suggest that NLRP1 is a complex receptor that responds to pathogens infection but also engages in maintaining host homeostasis." (PMID 38644450, 2024). "Nlrp1-/- mice displayed significantly higher parasite burden at the site of infection compared to C57BL/6 mice." (PMID 39250503, 2024). "NLRP1-dependent pyroptosis was probably too weak to substantially contribute to the observed cell death after infection with cytotoxic SFV." (PMID 36315050, 2023). "Influenza A virus (IAV) infection of cells caused GSDME activation, cytokine release, and cell death, in a PKR-dependent but NLRP1-independent manner, involving caspase-8 and caspase-3." (PMID 37680489, 2023). "ATP depletion induced by infection with Toxoplasma gondii or Listeria monocytogenes also activates the NLRP1 inflammasome." (PMID 35517498, 2022). "As for NLRP1, the Pyrin inflammasome senses an “alteration” induced by infection, namely the inactivation of Rho family small GTPases by bacterial Rho-modifying toxins." (PMID 35517498, 2022).
infection (continued). "To confirm that virally-produced 3Cpro, or the 3 CD precursor that can also carry out proteolytic cleavage during infection, is able to cleave NLRP1, we virally infected cells expressing either WT NLRP1 or the uncleavable (G131P) mutant." (PMID 33410748, 2021). "(D) Immunoblot depicting human NLRP1 cleavage at the indicated timepoints after infection with 250,000 PFU (MOI = ~1) CVB3 or EMCV." (PMID 33410748, 2021). "Infection of BMDMs from Nlrp1-/- and Mlkl-/- mice resulted in rapid cell death, with kinetics comparable to those observed in BMDMs from WT (B6J) mice." (PMID 32013758, 2020). "After infection of T. gondii, mGbp2B (also named Gbp1) can activate inflammasome complex signaling cascades, which leads to Nlrp1, Nlrp3, Nlrp4, and pro-caspase-1 degradation resulting in converting the cell death type from pyroptosis to apoptosis." (PMID 32731337, 2020). "Based on NLRP1 known function, we investigated the impact of the Toxo1 locus on parasite and host cell fate after ex vivo infection of peritoneal macrophages." (PMID 24699513, 2014). "We demonstrate that these events only take place after infection of pyroptosis-sensitive macrophages in a manner correlating with NLRP1 sequence." (PMID 24626226, 2014). "Following challenge with P. gingivalis at a multiplicity of infection (MOI) of 100, expression of the genes encoding NLRP3 and NLRP1 was increased, but with the gene encoding ASC being discordant and the gene encoding pro-IL-18 was downregulated." (PMID 25866631, 2014). "Next, we studied whether the endogenous NLRP1 inflammasome is activated upon infection with SFTSV in primary keratinocytes." (PMID 40608794, 2025). "Furthermore, in resting macrophages, as well as after infection clearance, NLRP1 inflammasome should be shut down, and its activation, downregulated." (PMID 38644450, 2024). "Consequently, the NLRP1-dependent phenotype observed following infection likely results from NLRP1 activation in other cell types." (PMID 39250503, 2024). "Our in vivo data demonstrated a role for the NLRP1 inflammasome in the control of infection." (PMID 39250503, 2024). "These variants were found in inflammasome genes (NLRP1/3 and CASP1), genes mediating inflammasome inactivation via auto- and mitophagy (RIPK2 and MEFV), and genes involved in the response to infection with DNA viruses (POLR3A, DHX58, and IFIH1) and type-1 interferons (TYK2 and PTPRC)." (PMID 37626706, 2023). "Infection of human keratinocytes with the model alphavirus SFV as well as cytosolic delivery of dsRNA was reported to activate NLRP1 inflammasomes by direct binding of dsRNA to NLRP1." (PMID 36315050, 2023). "This variation suggests that there is an ongoing evolutionary arms-race between viral proteins and the immune system: as viral proteins change and new ones emerge, NLRP1 rapidly evolves new tripwire sites that allow it to sense the infection and launch an inflammatory response." (PMID 33410748, 2021). "These variants were found in inflammasome genes (NLRP1/3, CASP1), genes mediating inflammasome inactivation via auto and mitophagy (RIPK2, MEFV), and genes involved in response to infection with DNA viruses (POLR3A, DHX58, IFIH1) and to type-1 interferons (TYK2, PTPRC)." (PMID 31235738, 2019). "In addition, NLRP1 silencing in human monocytes led to reduced production of IL-1β and greater rates of cellular infection." (PMID 30619358, 2018). "However, the F1 N terminus does function as an inhibitor of NLR family pyrin domain containing 1(NLRP1) inflammasome activity during infection." (PMID 28786952, 2017). "Furthermore, the HXB1 (NLRP1variant 5), HXB15 and HXB29 (NLRP1variant 1) RI strains also produced IL-1β after infection in a manner correlated with NLRP1 sequence and macrophage sensitivity to Toxoplasma." (PMID 24626226, 2014).
infection (continued). "During natural infection, the sand fly is transmitting salivary and gut products that also activate inflammasomes, thus in addition to NLRP1, other inflammasomes such as NLRP3 may be triggered in neutrophils following infection with L. mexicana in natural settings." (PMID 39250503, 2024). "Beyond the skin, NLRP1 is also basally expressed in tissues such as the gut and brain, which are sites of picornavirus replication where overactivation upon infection may result in immunopathology." (PMID 33410748, 2021). "Flow cytometry analysis at 3 dpi showed similar levels of infection (represented by GFP expression) of both control THP1/PMA and THP1/PMA/NLRP1 macrophages." (PMID 40920844, 2025). "We identify NLRP1-driven GSDMD pyroptosis in neutrophils as critical in the control of the early neutrophil pool, impacting the outcome of infection." (PMID 39250503, 2024). "Together, these results confirm that during L. mexicana infection in vivo, NLRP1-dependent caspase-1 activation of GSDMD, and subsequent pyroptosis control the neutrophil pool at the site of infection." (PMID 39250503, 2024). "Upon infection with Semliki Forest virus (SFV) with a positive-stranded RNA genome, NLRP1 undergoes self-cleavage by its function-to-find domain and leads to the generation of two chains of non-covalently associated polypeptides." (PMID 37515138, 2023). "UPEC significantly decreased the gene expression of CASP4, NLRP1, NLRC4, NLRP6 and AIM2 at MOI 1 and MOI 10 after 3 h of infection compared to unstimulated cells." (PMID 33318544, 2020). "For the case of Toxoplasma, inflammasome components NLRP1 and NLRP3 respond to infection resulting in IL-1β and IL-18 release, in turn promoting resistance to infection." (PMID 33505924, 2020). "Next to NLRP1, the AIM2 inflammasome also has relevant functions in human keratinocytes, since it senses infection by Herpes simplex virus (HSV)." (PMID 32640751, 2020). "Additionally, despite robust infection establishment in the presence of both pan-caspase (z-VAD) and caspase-1 (VX-765) inhibitors, IL-1β production was attenuated in THP1/PMA/NLRP1 macrophages compared to DMSO-treated infection control." (PMID 40920844, 2025). "Notably, the endogenous NLRP1 NT was reduced in primary keratinocytes following SFTSV infection, suggesting a mechanism of infection-induced degradation." (PMID 40608794, 2025). "Compared to control NLRP1+ THP-1/PMA cells, knockdown of MAVS or STING in NLRP1+ THP-1/PMA macrophages did not impact infection efficiency." (PMID 40920844, 2025). "Besides TLRs, S. mansoni infection also induced higher levels of inflammasome involved-molecules as NLRP1, NLRP3 and Caspase-1 in the second week of infection." (PMID 38896633, 2024). "NLRP1 and other leucine-rich repeat (LRR)-containing protein (NLR) family members can initiate the formation of inflammasomes which are cytosolic multi-protein complexes serving as sensors for infection and damage to illicit inflammatory response." (PMID 37658353, 2023). "Such additional signals may be provided by infection, as SFV infection was able to activate NLRP1 in both keratinocytes and HEK cells with reconstituted NLRP inflammasomes." (PMID 36315050, 2023). "Surprisingly, infection with the control virus VSV induced p38 phosphorylation as well, indicating that either p38 activation by alphaviruses differs from activation by VSV, or that VSV counteracts p38-dependent NLRP1 inflammasome stimulation." (PMID 36315050, 2023). "We observed accumulation of the expected cleavage product beginning at 6 hr post-infection when we infected cells expressing WT NLRP1 and no cleavage product when we infected cells expressing the 131P mutant." (PMID 33410748, 2021). "To ensure that we did not miss additional parasite effectors involved in NLRP1 inflammasome activation, we performed a genome-wide CRISPR screen in Toxoplasma followed by infection of LEW rat bone marrow-derived macrophages (BMDMs)." (PMID 38376248, 2024).
infection (continued). "Moreover, the expression of NLRP1 and NLRP4 mRNA was not induced following infection with either strain of EIAV." (PMID 40522989, 2025). "Eight hours after infection with CVB3, we observe robust release of active IL-1β into the culture supernatant when cells were transfected with WT NLRP1 but not the uncleavable mutant NLRP1." (PMID 33410748, 2021).
neurological diseases (10 papers, 2015 to 2024). "Recent studies demonstrated that the NLRP1 inflammasome is closely associated with neurological diseases such as AD." (PMID 34920732, 2021). "Therefore, inhibition of NLRP1 inflammasome may offer a new therapy for acidosis-induced neuronal damage in various acidosis-associated nervous system diseases." (PMID 26715049, 2015). "Some studies have shown that inhibiting NLRP1 can reduce the inflammatory pathway and disease progression of some nervous system diseases." (PMID 37214347, 2023). "The NLRP1 inflammasome play an important role in many neurological diseases, and studies in AD models indicate that the NLRP1 inflammasome is significantly upregulated in neurons." (PMID 34920732, 2021). "NLRP1 inflammasome-driven inflammatory response is believed to participate in many neurological disorders." (PMID 32513185, 2020). "NLRP1 inflammasome is also highly expressed in pyramidal neurons of the brain and has a key role in the pathogenesis of neurological disorders." (PMID 28732502, 2017). "In addition, inflammasome activation especially the NLRP1 is under current investigation across a broad spectrum of neurological diseases, including infections, acute sterile brain injury and chronic neurodegenerative diseases." (PMID 25626361, 2015). "Although current data regarding NLRP1 functions are far scarcer than those that described for other inflammasome, various studies have proposed its crucial role in neurological diseases such as neurodegenerative pathologies, in which inflammatory events and neuronal death have a clear causal role." (PMID 25626361, 2015). "Recent studies have shown that the activation of NLRP1 can generate a functional caspase-1-containing inflammasome in vivo to drive the proinflammatory programmed cell death termed ‘pyroptosis’, which has a key role in the pathogenesis of neurological disorders." (PMID 25626361, 2015). "Recent studies shown that the activation of NLRP1 inflammasome can generate a functional caspase-1-containing inflammasome in vivo to drive the proinflammatory programmed cell death termed ‘pyroptotic death’, which have key roles in the pathogenesis of neurological disorders." (PMID 25626361, 2015). "Thus, NLRP1 inflammasome may play an important role in nervous system diseases." (PMID 26715049, 2015).
skin disorder (6 papers, 2017 to 2023). Any deviation from the normal structure or function of the skin or subcutaneous tissue that is manifested by a characteristic set of symptoms and signs. "Among all NLR members (22 up to now), NLRP3, NLRP1, NLRC4, and NLRP6 represent the most studied inflammasomes, involved in many inflammatory tissues pathologies, where NLRP3, NLRP1, and NLRC4 are mainly related to autoinflammatory skin disorders." (PMID 38068996, 2023).
neurodegenerative disease (5 papers, 2020 to 2025). A disorder of the central nervous system characterized by gradual and progressive loss of neural tissue and neurologic function. "Dipeptidyl peptidase 9 and thioredoxin are examples of endogenous inhibitors that have been found to interact with NLRP1, raising the prospect of creating small-molecule medications that target NLRP1 to treat neurodegenerative diseases." (PMID 39861166, 2025). "Recent reports indicate that some biological and small-molecule inhibitors that target the NLRP1 inflammasome to treat neurodegenerative diseases are progressing to preclinical testing." (PMID 39861166, 2025). "Although NLRP1/3 is the most prevalent inflammasome in the CNS, NLRP3 is the one that has been studied the most, and it has been implicated in neurodegenerative diseases." (PMID 39861166, 2025). "In addition to NLRP3, other inflammasomes such as AIM2, NLRC4 and NLRP1 and their downstream effector molecules have been found to play pathological roles in neurodegenerative diseases." (PMID 39710713, 2024). "The focus of this study is on the NLRP1, NLRP3, and NLRC4 inflammasomes because they have garnered the most attention in the progression of neurodegenerative diseases." (PMID 31915018, 2020).
bacterial infection (4 papers, 2015 to 2021). "According to previous studies, various NLR-containing inflammasomes have been reported to be associated with bacterial infection, such as NLRP1, NLRP3, NLRC4, and NLRP6." (PMID 29616195, 2018). "Moreover, gene activation of inflammasome associated components such as NLRP1, ASC and caspase-1 has been described in response to bacterial infection in zebrafish (Danio rerio) and turbot (Scophthalmus maximus)." (PMID 33676414, 2021). "Whether the human NLRP1 inflammasome is also involved in ER stress-dependent caspase-4/5 activation and cell death in response to bacterial infections is currently under investigation." (PMID 26086088, 2015). "Low expression of NLRP1 and NLRP12 might be related to a risk of susceptibility for bacterial diseases, via reduced cleavage of pro-IL-1β and pro-IL-18 to produce mature isoforms, and via avoidance of infected macrophage lysis which contributes to pathology in TB." (PMID 31821366, 2019).
metabolic disease (4 papers, 2021 to 2026). A congenital disorder (due to inherited enzyme abnormality) or acquired (due to failure of a metabolically important organ) disorder resulting from an abnormal metabolic process. "Several studies have involved NLRP1 having either a protective or worsening role in a variety of metabolic diseases." (PMID 33682108, 2021). "Overall, it is clear that NLRP1 inflammasome has a crucial role as a sensor of cellular stress, as well as glucose and lipid metabolic perturbation, maintaining cellular homeostasis to prevent a wide range of metabolic diseases." (PMID 33682108, 2021). "In summary, studies should be carried out to illustrate the role and mechanism of other inflammasomes, including AIM2, NLRP1, NLRP6 and NLRC4 inflammasomes, in metabolic disorders." (PMID 40433411, 2025).
infectious disease (3 papers, 2021 to 2025). A disorder directly resulting from the presence and activity of a microbial, viral, or parasitic agent in humans. "In this study, the NLRP1 A/T rs12150220 genotype was associated with protection against infectious diseases." (PMID 33972620, 2021). "NLRP1 and NLRC4 have classically been associated with inflammatory and infectious diseases." (PMID 40332346, 2025). "Additional approaches using tissue-specific knockout models and inducible NLRP1 mutants may help address these pressing questions and guide therapeutic targeting of NLRP1 in autoinflammatory and infectious diseases." (PMID 41062723, 2025). "The NLR family pyrin domain-containing protein 1 (NALP/NLRP1) and protein 3 (NLRP3), as well as NLR family CARD domain-containing protein 4 (NLRC4) inflammasomes, are the best-known inflammasomes in immune and infectious diseases." (PMID 40332346, 2025).
immune dysfunction (2 papers, 2018 to 2025). "Accumulating data suggest that inflammasomes, mainly NLRP3, NLRP1, and AIM2, are involved in the generation of tissue damage and immune dysfunction after trauma." (PMID 30166988, 2018).
inflammation (2 papers, 2020 to 2024). Aberrant reaction of the microcirculation characterized by movement of fluid and leukocytes from the blood into extravascular tissues. "Among these, NOD-like receptors (NLRs), including NOD1, NLRP1, and NLRP3, serve as vital interfaces between microbiota and systemic chronic inflammation." (PMID 38336763, 2024).
kidney disease (2 papers, 2018 to 2021). "Although there are few studies on the NLRP1 inflammasome, many results have confirmed its important role in the pathogenesis of kidney disease." (PMID 34222479, 2021).